CETP (cholesteryl ester transfer protein)
Diseases named in the same sentence as CETP in open-access papers (continued):
Sharing a sentence is not in itself a finding about the gene and the disease.
atherosclerosis (continued). "Strikingly, it appears that the balance between protective and deleterious effects of apoC1 mostly rely on the presence of CETP in the experimental models, as illustrated, among others by opposite effects human apoC1 on atherosclerosis between mice and rabbits." (PMID 36471375, 2022). "Plasma cholesteryl ester transfer protein (CETP) activity diminishes HDL-cholesterol levels and thus may increase atherosclerosis risk." (PMID 36139808, 2022). "A study explored whether CETP was related to atherosclerosis through its role in HDL-C and low-density lipoprotein metabolism." (PMID 35514441, 2022). "Here, we investigated whether Proc-silencing allows APOE*3-Leiden.CETP mice, like Apoeˉ/ˉ mice, to feature thrombosis as final stage of atherosclerosis." (PMID 34052976, 2021). "Interestingly, genetic ablation of CETP gene in the rabbit model demonstrated athero-protective effects, suggesting a potential therapeutic target for atherosclerosis treatment." (PMID 34445123, 2021). "The observations demonstrate that CETP deficiency is not correlated with atherosclerosis susceptibility in the absence of other major CV risk factors." (PMID 33807918, 2021). "Further studies are needed to answer whether an increase in plasma HDL-C levels following a reduction in CETP mass and activity could prevent atherosclerosis progression and related cardiovascular events." (PMID 33799675, 2021). "Similar to observations in human studies, the impact of transgenic CETP expression in mice with regard to atherosclerosis risk factors is not consistent." (PMID 35082691, 2021). "On the other hand, Apoe3Leiden transgenic mice overexpressing human cholesteryl ester transfer protein (CETP) treated with NA also showed reduced atherosclerosis development concomitant with enhanced very-low density lipoprotein clearance and low CETP activity resulting in higher HDL-C." (PMID 34943043, 2021). "The aim of the study was to investigate whether silencing of anticoagulant Protein C (Proc) allows APOE*3-Leiden.CETP mice to feature thrombosis as a final stage of atherosclerosis." (PMID 34052976, 2021). "The impact of cholesteryl ester transfer protein (CETP) on atherosclerosis is highly debated." (PMID 33799675, 2021). "In this study, we investigated whether continuous artificial light exposure aggravates atherosclerosis by exposing APOE*3-Leiden.CETP mice to either normal LD cycles or LL conditions." (PMID 32915671, 2020). "Tert-butyl-4-(2-hydroxyethyl)-4-(pyrrolidin-1-yl)-piperidine-1-carboxylate (PYPEP), which is another PPARδ agonist, inhibited atherosclerosis in human apolipoprotein B100 and cholesteryl ester transfer protein double-transgenic mice by improving the serum lipoprotein profiles." (PMID 32258142, 2020). "In addition, double and triple treatments improve lesion morphology and composition in APOE*3-Leiden.CETP mice with pre-existent atherosclerosis." (PMID 31843957, 2020). "Our CETP results indicated that higher CETP expression is associated with lower HDL levels, which has been previously observed extensively within humans and has become a potential drug target for preventing atherosclerosis." (PMID 31393916, 2019). "Chronic OSM administration in APOE*3Leiden.CETP mice reduced atherosclerosis development." (PMID 31461490, 2019). "Thus, CETP inhibition was perceived as a straightforward therapeutic approach against atherosclerosis, but in fact, it turned out to be a more complicated issue due to the genetic variation and pleiotropic actions of CETP." (PMID 31779116, 2019). "Conversely, deficiency in cholesteryl ester transfer protein (CETP) activity resulting in increased HDL levels does not unequivocally protect against atherosclerosis." (PMID 31323735, 2019). "Given the strong effects of MOS on both plasma TC and atherosclerosis development, comparable to the effects of statins in E3L.CETP mice, dietary MOS might present a novel approach in the prevention of atherosclerosis development and progression." (PMID 29665623, 2018).
atherosclerosis (continued). "As atherosclerosis is accelerated both by hyperlipidemia and inflammation, we aim to determine the effect of dietary MOS on atherosclerosis development in hyperlipidemic ApoE*3‐Leiden.CETP (E3L.CETP) mice, a well‐established model for human‐like lipoprotein metabolism." (PMID 29665623, 2018). "The involvement of CETP in atherosclerosis, whether this protein is beneficial or pro-atherogenic, is largely controversial." (PMID 30342531, 2018). "CETP may be deleterious for atherosclerosis, but it is also likely that high levels of CETP are the result rather than the cause of dyslipidemia." (PMID 29317793, 2017). "In rabbits, CETP inhibition led to a reduction in atherosclerosis." (PMID 28342064, 2017). "Therefore, rabbits have been extensively used for investigating the therapeutic effects of CETP inhibitors on the inhibition of atherosclerosis." (PMID 28767652, 2017). "Most but not all studies in transgenic (Tg) mice have shown that CETP inhibition reduces atherosclerosis development, and the role of CETP in atherosclerosis requires further deep investigation because of the differences in the lipid metabolism of mice and humans." (PMID 29317793, 2017). "The overall role of CETP in atherosclerosis is complex, and whether CETP is an antiatherogenic or proatherogenic protein has been debated for many years." (PMID 28893253, 2017). "Cholesteryl ester transfer protein (CETP) is an important factor in regulating lipoprotein metabolism, which transfers cholesterol ester (CE) from HDL to lipoproteins of lower density and is closely linked to atherosclerosis." (PMID 27378433, 2016). "However, another in vivo study reported that CETP expression reduced atherosclerosis in lecithin cholesterol acyltransferase (LCAT) transgenic mice and a further study revealed that CETP offset the deleterious effect of LCAT." (PMID 25366166, 2014). "The history of the hypothesis that CETP inhibition will prevent atherosclerosis can be summarised thus." (PMID 25187879, 2014). "The interest towards CETP and its lipid transfer functions came to the forefront after notable associations between decreased CETP activity, decreased LDL-cholesterol level, increased HDL-cholesterol level, and resistance to atherosclerosis." (PMID 25412509, 2014). "These associations between CETP and plaque progression have also been observed in atherosclerosis studies conducted in nonhuman primates, in which the CETP protein was predictive of coronary artery intimal area." (PMID 23801661, 2013). "Furthermore, these results are consistent with other atherosclerosis studies in tg mice, in which CETP expression was proatherogenic, and in cholesterol-fed rabbits, in which administration of a CETP ASO also reduced aortic cholesterol." (PMID 23801661, 2013). "CETP quantity and activity also reflect atherosclerosis status." (PMID 24204732, 2013). "In this study, we hypothesized that xanthohumol prevents atherosclerosis in vivo and used CETP-transgenic mice (CETP-Tg mice) to evaluate xanthohumol as a functional agent." (PMID 23166663, 2012). "Thus, in this study, we investigated the effect of xanthohumol on lipoprotein metabolism and anti-atherosclerosis induced by HCD using CETP-Tg mice." (PMID 23166663, 2012).
atherosclerosis (continued). "Many studies proved that the ApoE*3Leiden.CETP transgenic mouse is a valuable model to investigate the pathogenesis of vascular atherosclerotic lesion development and the effect of combination therapies on dyslipidemia and atherosclerosis." (PMID 21611179, 2011). "The model described in this article may prove to be a valuable tool for studying the impact of imbalanced postprandial lipemia, impaired hydrolysis of TG or metabolic adaptions in pregnancy on LDL and HDL composition, and CETP’s role in atherosclerosis and other metabolic disorders." (PMID 40562102, 2025). "In this context, E3L.CETP mice fed chow diet represent a unique model of the age-dependent trajectory for the accelerated progression of endothelial dysfunction, induced by mild hyperlipidaemia superimposed on ageing that occurs before atherosclerosis development." (PMID 40240752, 2025). "Blocking CETP could be a potential choice against atherosclerosis." (PMID 40823653, 2025). "Therefore, high CETP activity may decrease HDL levels and cause cholesterol accumulation in LDL and VLDL particles, thereby increasing the risk of atherosclerosis." (PMID 39765884, 2024). "Genetic deficiency of CETP activity, and its association with an improved lipid profile (decreased LDL cholesterol (LDL-C) and increased HDL cholesterol [HDL-C]) resulting in reduced premature atherosclerosis, was first described in Japanese subjects in the mid-1980s." (PMID 38133847, 2024). "Interestingly, CETP is present and active in all primates, rabbits, and hamsters, but is lacking in the plasma of most other species; this phenomenon directly influences the development of resistance to atherosclerosis in opposing species." (PMID 38786974, 2024). "CB1 receptor antagonism may be a potential method of preventing cardiovascular diseases, possibly through decreasing lipids as well as inflammation, since E3L.CETP mice are a well-established model for human-like lipoprotein metabolism and atherosclerosis formation." (PMID 36768835, 2023). "Cholesteryl ester transfer protein (CETP) (iHS score of rs12597002:1.6131, and rs291044: 1.6484) is a liver-synthesized glycoprotein, and some studies have shown that CETP inhibitors can be used for the prevention and treatment of coronary heart disease and atherosclerosis." (PMID 36721228, 2023). "Given that inflammation plays a key role in the initiation and progression of atherosclerosis, we may conclude that CETP, in the context of preserved Nnt expression, contributes to the development of a less detrimental and more stable type of atherosclerotic lesion." (PMID 37892238, 2023). "It is hypothesized that species which possess CETP, such as rabbits, are much more susceptible to the development of atherosclerosis than species that do not possess CETP." (PMID 34849601, 2022). "E3L.CETP mice, due to their genetic APOE*3Leiden mutation, have an impaired clearance of apoB-containing lipoproteins, thereby mimicking the slow clearance observed in humans and resulting in a mouse model that develops hyperlipidemia and atherosclerosis upon saturated fat and cholesterol feeding." (PMID 33658534, 2021). "Moreover, we have found a correlation between the levels of different inflammatory cytokines and CETP levels after diet, in particular lower IL-8 and MIP-1b levels were associated with lower CETP level, which has been associated with the formation of HDL and a reduced the risk of atherosclerosis." (PMID 33686615, 2021). "However, in apoCIII-transgenic hypertriglyceridemic mice or SR-BI knockout mice, CETP expression limits atherosclerosis progression, suggesting CETP overexpression could be atheroprotective in the presence of hypertriglyceridemia." (PMID 35082691, 2021). "Second, we did not test for all CETP gene variants, which might have compromised the possibility to better evaluate the relationship between CETP and atherosclerosis." (PMID 33799675, 2021).
atherosclerosis (continued). "Therefore, CETP expression may play an important role in the prevention of atherogenic lipoprotein profiles and atherosclerosis in diabetic mice." (PMID 31597401, 2019). "Although each species has different advantages in terms of their usefulness in lipid metabolism and atherosclerosis, rabbits as well as hamsters may be superior to guinea pigs if one aims to examine the functions of CETP and its relationship with atherosclerosis." (PMID 28767652, 2017). "Furthermore, the relationship of CETP and atherosclerosis (AS) has been controversial." (PMID 28893253, 2017). "Finally, it remains to be established whether increased CETP expression can be used for treating atherosclerosis in humans." (PMID 29317793, 2017). "The present studies may have implications for CETP inhibition in atherosclerosis." (PMID 29317793, 2017). "Therefore, through inhibition of CETP, could increase the level of LDL smaller that would increase the risk of atherosclerosis." (PMID 26535185, 2015). "These actions suggest that CETP inhibition could prevent atherosclerosis and prevent CHD." (PMID 18922179, 2008). "Advancements in gene editing techniques, particularly zinc finger nuclease, helped to create more advanced genetic models, which include also models of atherosclerosis, such as APOE, APOC3 and CETP knockout (KO) rabbits." (PMID 39364866, 2025). "Primarily, studies have suggested that certain antigens, such as ox-LDL, ApoB-100, CETP, PCSK9, HSP60, MHC-II-derived peptides, and interleukins, are involved in atherosclerosis." (PMID 40823653, 2025). "Next, the effect of Vwf-silencing was also assessed in the aortic root area of the heart, which is known to be the atherosclerosis and atherothrombosis-prone location in the APOE∗3-Leiden.CETP mice." (PMID 40093962, 2025). "CETP mice incorporate human CETP (cholesterol ester transfer protein plasma; OMIM: 118470), enabling LDL-driven atherosclerosis and human-like drug responses." (PMID 40722594, 2025). "The APOE*3-Leiden.CETP model is characterized by substantial genetic overlap with human NASH and atherosclerosis." (PMID 39404395, 2024). "In the previous sections we have highlighted the most frequently used mouse models in atherosclerosis research, while there are many other available mouse models, for instance mice expressing both human APOB and CETP." (PMID 38428154, 2024). "APOE*3-Leiden.CETP mice were also employed to demonstrate the efficacy of anti-PCSK9 therapies for lowering LDL-C and TGs, which translated to reduced atherosclerosis development in the aortic root." (PMID 39404395, 2024). "Conversely, transient inhibition of CETP in animal models, using monoclonal antibodies, small molecules, or antisense oligonucleotides, results in elevated HDL-C levels and reduced atherosclerosis progression." (PMID 39766344, 2024). "CETP and APOC3 inhibitors represent promising therapeutictargets in the management of hyperlipidemia and atherosclerosis." (PMID 39228495, 2024). "Blocking CETP to inhibit proatherogenic lipoprotein remodeling represents a promising strategy for mitigating cardiovascular diseases (CVD), particularly atherosclerosis cardiovascular disease (ASCVD), which is the leading cause of death in many countries." (PMID 37569628, 2023).
atherosclerosis (continued). "Thus, the observed CETP-dependent mitochondrial antioxidant effects and downregulation of pro-inflammatory genes in macrophages might be relevant to the initiation and progression of atherosclerosis." (PMID 36139808, 2022). "Overexpression of CETP decreases serum HDL-C levels and increases the accumulation of macrophage-derived foam cells in lesions, thereby contributing to atherosclerosis." (PMID 35265678, 2022). "In contrast, transgenic mice expressing both human mutant APOE form APOE*3-Leiden and human cholesteryl ester transfer protein (CETP) i.e. APOE*3-Leiden.CETP mice, feature a moderate and easy modifiable hyperlipoproteinemia and atherosclerosis phenotype." (PMID 34052976, 2021). "CETP is thus thought to be a target for treatment of increased LDL-C levels and inhibiting atherosclerosis." (PMID 33499410, 2021). "Together, these results suggest that CETP expression leads to EC dysfunction and may play a role in the setting of EC activation, which is a process that promotes the expression of adhesion molecules, resulting in the recruitment of monocytes/macrophages that could accelerate atherosclerosis." (PMID 33430172, 2021). "Reports have also emphasized that such compounds are active inhibitors in cholesteryl ester transfer protein (CETP) and acyl-CoA:cholesterol acyltransferase (ACAT), which promote the therapeutic potential of atherosclerosis." (PMID 32627761, 2021). "Considering that global CETP inhibition has not reached the expected benefits, the present results suggest that endothelial CETP inhibition may be a good strategy to decrease atherosclerosis risk." (PMID 33430172, 2021). "Transgenic mice expressing both the human mutant apolipoprotein E form APOE*3-Leiden and human cholesteryl ester transfer protein (CETP), i.e. APOE*3-Leiden.CETP mice, feature a moderate hyperlipoproteinemia and atherosclerosis phenotype." (PMID 34052976, 2021). "A CETP inhibitor molecule known as JTT-705 and shown to decrease atherosclerosis in rabbits was found to inhibit CETP activity by 30% to 40%." (PMID 30704580, 2019). "Next, we explored the effect of long-term OSM administration on endothelial activation, atherosclerosis development and lesion composition in APOE*3Leiden.CETP mice, a translational model for human lipoprotein metabolism and atherosclerosis development." (PMID 31461490, 2019). "In the presence of CETP, AET positively influences gene expression in the arterial wall and macrophages of CETP-tg mice contributing to the RCT and prevention of atherosclerosis." (PMID 29867549, 2018). "It was reported that dyslipidemic patients would have an elevated CETP concentration and/or an accelerated rate of net transfer of cholesteryl esters from HDL to apoB-containing lipoproteins as well as accelerated atherosclerosis." (PMID 29317793, 2017). "Exendin-4 (50 μg/kg/day) treatment resulted in a reduction of atherosclerosis development and the number of monocytes adhering to the endothelium wall in the aortic root in western-type diet-fed APOE∗3-Leiden.CETP(E3L.CETP) mice." (PMID 27110066, 2016). "While industry progressed to clinical studies, academics sought to clarify the relations of CETP activity to RCT and atherosclerosis." (PMID 26236237, 2015). "Alirocumab dose-dependently decreases plasma lipids and, as a result, atherosclerosis development, and it enhances the beneficial effects of atorvastatin in APOE*3Leiden.CETP mice." (PMID 25139399, 2014). "The aim of this study was to investigate the effects of two dosages of alirocumab alone and in combination with atorvastatin on plasma lipids, atherosclerosis development, and lesion composition in APOE*3Leiden.CETP mice." (PMID 25139399, 2014). "These included the Stop Atherosclerosis in Native Diabetics Study (SANDS) and a study evaluating the CETP inhibitor dalcetrapib." (PMID 23893306, 2013).